NKILA (NF-kappaB interacting lncRNA)
Diseases named in the same sentence as NKILA in open-access papers (continued):
Sharing a sentence is not in itself a finding about the gene and the disease.
breast carcinoma (continued). "Our previous study reported a novel mechanism of action for lncRNA that lncRNA NKILA could directly interact with signaling protein NF-κB by blocking the IKK phosphorylating sites of IκB and therefore inhibiting NF-κB mediated breast cancer cell apoptosis and migration." (PMID 27613832, 2016).
laryngeal carcinoma (9 papers, 2018 to 2024). Carcinoma that arises from the laryngeal epithelium. "The data indicate that NKILA can suppress laryngeal cancer cell proliferation and migration; however, the underlying mechanism still remains unclear." (PMID 29573243, 2018). "For example, DLX6-AS1, NEAT1, ZFAS1 and NKILA regulate the progression of laryngeal cancer through different regulatory mechanisms." (PMID 38967843, 2024). "More in detail, NKILA functioned as a tumor suppressor by inhibiting laryngeal cancer cell viability and migration and promoting apoptosis through NF-κB modulation." (PMID 35406495, 2022). "P65 positively regulates the NKILA expression, however, NKILA inhibits the translocation of P65 to reduce the resistance of cells to X-ray radiation in laryngeal cancer." (PMID 31430288, 2019). "NKILA overexpression significantly suppressed the cell viability and migration, whereas promoted the apoptosis of laryngeal cancer cell, indicating its potential as a tumor suppressor." (PMID 29573243, 2018). "Herein, we demonstrated a low NKILA expression in laryngeal cancer and its correlation with shorter overall survival in patients with laryngeal cancer." (PMID 29573243, 2018). "Taken together, we provided experimental and theoretical basis for understanding the mechanism of NKILA‐mediated laryngeal cancer radioresistance regulation." (PMID 29573243, 2018). "Consistent with previous studies in other cancers 16, 17, 18, NKILA expression was dramatically down regulated in laryngeal cancer tissues compared to that in normal tissues." (PMID 29573243, 2018). "We have revealed that NKILA suppresses the cell proliferation and migration of laryngeal cancer cells; next, we assessed the effect of NKILA on the radioresistance of laryngeal cancer cells." (PMID 29573243, 2018). "Through combining with NF‐κB: IκB complex, NKILA reduced IκB phosphorylation and NF‐κB activation, inhibited p65 nuclear translocation, thereby sensitizing laryngeal cancer to radiotherapy." (PMID 29573243, 2018). "Herein, we also validated the combination between NKILA and NF‐κB: IκB complex in laryngeal cancer cell lines." (PMID 29573243, 2018). "In order to evaluate the role of NKILA in laryngeal cancer, we first determined NKILA expression in normal and laryngeal cancer tissues using real‐time PCR assays." (PMID 29573243, 2018). "The data indicate that NKILA knockdown can enhance the resistance of laryngeal cancer to X‐ray radiation." (PMID 29573243, 2018). "Herein, NKILA expression was significantly down regulated in laryngeal cancer; particularly, NKILA expression was much lower in patients with advanced N stages and advanced clinical stages." (PMID 29573243, 2018). "In conclusion, NKILA can serve as a promising agent of enhancing the cytotoxicity of X‐ray radiation on laryngeal cancer and addressing the radioresistance of laryngeal cancer." (PMID 29573243, 2018). "NKILA can serve as a promising agent of enhancing the cytotoxicity of X‐ray radiation on laryngeal cancer and addressing the radioresistance of laryngeal cancer." (PMID 29573243, 2018). "In the present study, we demonstrated that NKILA expression was significantly down regulated in laryngeal cancer tissues, particularly in tissues derived from patients in advanced N stages or clinic stages." (PMID 29573243, 2018). "However, some elevated expression of LINC00312 in NPC, TPTEP1 in glioma, and NKILA in laryngeal carcinoma was found to be related to radiosensitivity." (PMID 36323697, 2022). "As expected, the data of luciferase reporter gene and ChIP assays revealed that NF‐κB could bind to the promoter region of NKILA, thereby activating its transcriptional activity and promoting NKILA expression in laryngeal cancer cell lines." (PMID 29573243, 2018). "Patients with low NKILA expression obtained a significantly shorter overall survival, suggesting that the NKILA expression decrease may contribute to the poor prognosis of patient with laryngeal cancer." (PMID 29573243, 2018).
laryngeal carcinoma (continued). "Herein, we validated whether NKILA can inhibit NF‐κB signaling through the inhibition of IκB in laryngeal cancer cell lines." (PMID 29573243, 2018). "Moreover, NKILA also inhibited p65 nuclear translocation in laryngeal cancer cells exposed to 8 Gy radiation, thereby enhancing the cytotoxicity of X‐ray radiation on cancer cells." (PMID 29573243, 2018). "After NKILA knockdown, the cytotoxicity of X‐ray radiation on laryngeal cancer cell was partially reversed, manifested as promoted cell viability and migration and suppressed apoptosis of laryngeal cancer cell." (PMID 29573243, 2018). "Based on the previous findings, we hypothesized that NKILA might play a potential role in laryngeal cancer in a NF‐κB‐dependent manner." (PMID 29573243, 2018). "However, the role and molecular mechanism of NKILA in laryngeal cancer progression still remain unclear." (PMID 29573243, 2018). "The data suggest that NKILA might serve as a tumor suppressor laryngeal cancer." (PMID 29573243, 2018). "We have found that NKILA reduces the protein levels of cytoplasm and nucleus p65; next, we validated whether NKILA overexpression could inhibit p65 nuclear translocation, thereby affecting the resistance of the laryngeal cancer cell to X‐ray radiation." (PMID 29573243, 2018). "Contrary to tumor cell viability and migration, laryngeal cancer cell apoptosis was significantly promoted by 8 Gy radiation while slightly reduced by NKILA knockdown; the promotive effect of X‐ray radiation on tumor cell apoptosis could be partially reversed by NKILA knockdown." (PMID 29573243, 2018). "For instance, NKILA, MSC-AS1, lncRNA-ATB, RP11-159K7.2, as well as LINC00152 have been reported to modulate laryngeal cancer progression via different regulatory mechanisms." (PMID 36224753, 2022). "Two laryngeal cancer cell lines, HEp‐2 and TU212, were infected with NKILA‐inhibiting (LV‐shNKILA‐1, LV‐shNKILA‐2, or LV‐shNKILA‐3) or overexpressing lentivirus (LV‐NKILA) to achieve NKILA knockdown or overexpression, as confirmed using real‐time PCR assays." (PMID 29573243, 2018). "Subsequently, upregulated NKILA then inhibits IκB phosphorylation and NF‐κB activation, thus forming a negative feedback loop to sensitize laryngeal cancer cell to X‐ray radiation." (PMID 29573243, 2018). "NF‐κB binds to the promoter region of NKILA to activate its transcriptional activity, upregulated NKILA then inhibits IκB phosphorylation and NF‐κB activation, thus forming a negative feedback loop to sensitize laryngeal cancer cell to X‐ray radiation." (PMID 29573243, 2018).
lung cancer (9 papers, 2018 to 2025). A malignant neoplasm involving the lung. "Through functional assays in breast and lung cancer, they uncovered that NKILA sensitizes T cells (cytotoxic CD8+ T cells and CD4+ Th1 cells) to activation-induced cell death (AICD), and high expression of NKILA was associated with reduced patient survival." (PMID 37346034, 2023). "NKILA expression shows a great downregulation in lung cancer tissues than the corresponding normal tissues." (PMID 35237359, 2022). "Interestingly, tumor-specific cytotoxic T cells and TH1 isolated from breast and lung cancer patients display a high expression of NKILA and a high sensitivity to AICD." (PMID 37782337, 2024). "lncRNA NKILA overexpression sensitizes tumor-specific cytotoxic T-lymphocytes and type 1 helper T cells, resulting in activation-induced cell death and cancer immune evasion in breast and lung cancers." (PMID 34958632, 2021).
hepatocellular carcinoma (8 papers, 2016 to 2023). A malignant tumor that arises from hepatocytes. "As previously reported, NKILA represses NF-κB activation by directly or indirectly inhibiting phosphorylation of IκBα in breast and hepatocellular carcinoma." (PMID 31430288, 2019). "Besides, in hepatocellular carcinoma, lncRNA NKILA has been reported for suppressing NF-κB/Slug pathway mediated with epithelial-mesenchymal transition to inhibit tumor metastasis." (PMID 34714775, 2021). "In hepatocellular cancer(HCC), NKILA could enhance the anticancer effect of safrole by regulating the NF‐κB signaling pathway." (PMID 32249459, 2020).
cholangiocarcinoma (7 papers, 2022 to 2025). A carcinoma that arises from the intrahepatic biliary tree (intrahepatic cholangiocarcinoma) or from the junction, or adjacent to the junction, of the right and left hepatic ducts (hilar cholangiocarcinoma). "Cholangiocarcinoma cell lines were cultured in vitro and the transplanted tumor model was constructed in vivo to study the role of NKILA in ICC." (PMID 41498025, 2025). "Our previous study demonstrated the nuclear transcription factor NF‐κB interacting long noncoding RNA (lncRNA) (NKILA) as a regulator of cholangiocarcinoma cell growth." (PMID 41498025, 2025). "m5C and m6A modifications of LncRNA NKILA have been found to facilitate cholangiocarcinoma growth and metastasis through the miR-582-3p-YAP1 axis." (PMID 37308824, 2023). "In cholangiocarcinoma (CCA) cell lines, the lncRNA NF-kappa B interacting lncRNA (NKILA), which is overexpressed and associated with reduced overall survival of CCA patients, was modified by m5C which stabilized NKILA." (PMID 37628704, 2023). "Based on the UALCAN analysis, we found that NKILA, MTX1, and TOMM40 were highly expressed in cholangiocarcinoma." (PMID 41498025, 2025). "LncRNA NKILA is regulated by the m5c methyltransferase NSUN2 to increase m5C levels, which promotes NKILA interaction with YBX1 for regulating the progression of cholangiocarcinoma." (PMID 37403043, 2023). "In contrast, NKILA interacts with mir-582-3p regulated by m6A methyltransferase METTL3 and inhibits its expression, thereby accelerating cholangiocarcinoma progression through YAP1." (PMID 36333719, 2022). "In cholangiocarcinoma, the m5C methyltransferase NSUN2 interacts with the lncRNA NKILA to increase its m5C level and promote its interaction with YBX1." (PMID 36333719, 2022).
glioma (5 papers, 2020 to 2024). A benign or malignant brain and spinal cord tumor that arises from glial cells (astrocytes, oligodendrocytes, ependymal cells). "Rg3 suppresses NKILA accumulation and reverses its stimulation of the Warburg effect and angiogenesis in glioma." (PMID 39036728, 2024). "The NF-κB-interacting lncRNA NKILA is significantly upregulated in gliomas, and higher NKILA levels are correlated with poorer patient prognosis." (PMID 34803608, 2021). "To further investigate the role of NKILA in gliomas, we performed gene set enrichment analysis (GSEA) on the RNA sequencing (RNA-seq) profiles of the glioma cohort from TCGA database, and found that the level of NKILA positively correlated with hypoxia." (PMID 32382013, 2020). "Surprisingly, this study showed that NKILA is significantly upregulated in gliomas, and the increased levels of NKILA were correlated with a decrease in patient survival time." (PMID 32382013, 2020). "To investigate the role of NKILA in gliomas, we used qRT-PCR to measure the expression levels of NKILA in 15 clinical GBM tissue samples, 10 clinical LGG tissue samples, and 10 normal brain tissue samples." (PMID 32382013, 2020). "The results showed that inhibition of HIF-1α expression in glioma cells with overexpression of NKILA can effectively reverse the stimulation of the Warburg effect and angiogenesis in gliomas." (PMID 32382013, 2020). "Collectively, these data showed that NKILA overexpression contributes to angiogenesis and the Warburg effect in gliomas." (PMID 32382013, 2020). "We also analyzed the RNA profiles and clinical data of 669 patients with gliomas from TCGA database; the analyses indicated that NKILA expression was significantly correlated with tumor grade and type." (PMID 32382013, 2020). "We tested the effect of NKILA on the overall regulation of glycolytic flux and mitochondrial respiration in glioma cells by measuring changes in ECAR and OCR, respectively." (PMID 32382013, 2020). "qRT-PCR showed that NKILA expression in glioma cell lines was suppressed by 20(S)-Rg3 by as much as 80%." (PMID 32382013, 2020). "NKILA increased the expression level of hypoxia-inducible factor-1α, and the activity of the hypoxia pathway in gliomas." (PMID 32382013, 2020). "In this study, we found that NKILA is significantly upregulated in clinical glioma tissue samples and glioma cell lines." (PMID 32382013, 2020). "We found that downregulation of NKILA expression in glioma cells significantly decreased HUVEC tube formation in LN229 and T98G cell lines." (PMID 32382013, 2020). "Western blotting showed that when NKILA was overexpressed in U87 and A172 cells, the activity of the NF-kappa B pathway in glioma cells decreased significantly." (PMID 32382013, 2020). "High levels of NKILA expression were correlated with high-grade glioblastomas and recurrent gliomas." (PMID 32382013, 2020). "NKILA stimulates activity of the hypoxia signaling pathway, the Warburg effect, and angiogenesis in gliomas, whereas 20(S)-Rg3 suppresses the expression of NKILA and reverses its stimulation of the Warburg effect and angiogenesis in gliomas." (PMID 32382013, 2020). "Our study of gliomas suggests that NKILA is a potential therapeutic target and 20(S)-Rg3 is a potential therapeutic agent." (PMID 32382013, 2020). "In gliomas, Rg3 counters lncRNA NKILA-induced hypoxia, the Warburg effect, and angiogenesis." (PMID 39036728, 2024). "In addition, we measured NKILA expression levels in eight human glioma cell lines, and in the normal astrocyte human cell line SVGp12." (PMID 32382013, 2020). "Furthermore, immunohistochemical staining showed that GLUT1, HK2, PKM2, LDH, and MCT1 were significantly downregulated in the 20(S)-Rg3 group, confirming that downregulation of NKILA by 20(S)-Rg3 reversed the Warburg effect in glioma cells in vivo." (PMID 32382013, 2020).
glioma (continued). "In addition, we show that a monomer from herbal medicine suppresses NKILA accumulation and reverses its stimulation of the Warburg effect and angiogenesis in gliomas." (PMID 32382013, 2020). "In contrast to studies on other types of cancer, these data suggest that NKILA may stimulate tumor progression in gliomas." (PMID 32382013, 2020). "Interestingly, we also observed that 20(S)-Rg3 significantly suppressed the expression of NKILA in glioma cells." (PMID 32382013, 2020). "Firstly, we overexpressed NKILA or NC in U87 and A172 cells with lentivirus (Lv-O.E.-NC or Lv-O.E.-NKILA), 48 h later, we determined the intracellular and extracellular (supernatant of glioma cells) NKILA levels in U87 and A172 cells with different transfection by qRT-PCR." (PMID 32382013, 2020). "This study showed for the first time that the lncRNA NKILA is upregulated in glioma tissues and cells, and increased expression of NKILA may be correlated with a poorer prognosis in patients with gliomas." (PMID 32382013, 2020). "Furthermore, GSEA of glioma RNA-seq profiles showed that NKILA expression was positively correlated with the activity of the hypoxia pathway." (PMID 32382013, 2020). "To confirm that NKILA is involved in regulating the hypoxia pathway in glioma cells, we transfected glioma cells with lentivirus to downregulate or overexpress NKILA, and used western blotting analyses to assess changes in the expression of key proteins in the hypoxia pathway." (PMID 32382013, 2020). "Furthermore, RNA profiling and clinical data from 669 patients with gliomas from The Cancer Genome Atlas (TCGA) database showed that high levels of NKILA correlated with high-grade glioblastomas and recurrent gliomas." (PMID 32382013, 2020). "LDH activity was also positively correlated with the expression of NKILA in glioma cells." (PMID 32382013, 2020). "Furthermore, we demonstrated that NKILA enhances the Warburg effect and angiogenesis in gliomas both in vitro and in vivo." (PMID 32382013, 2020). "Subsequent in vitro and in vivo experiments assessed the biological role of NKILA in gliomas, and integrative analysis revealed that NKILA may enhance the Warburg effect and angiogenesis in gliomas via the hypoxia pathway, thereby driving tumor progression." (PMID 32382013, 2020). "Therefore, this study not only identified NKILA as a potential therapeutic target in gliomas, but also demonstrated a practical approach to treatment." (PMID 32382013, 2020). "NKILA can also inhibit IkB phosphorylation and NF-kappa B activation in many types of malignant tumors, but its effects in gliomas remain unclear." (PMID 32382013, 2020). "NKILA transcript levels were generally higher in the glioma cell lines than in SVGp12." (PMID 32382013, 2020). "In addition, we showed that a 20(S)-Rg3 monomer suppresses NKILA accumulation and reverses its stimulation of the Warburg effect and angiogenesis in gliomas, both in vitro and in vivo." (PMID 32382013, 2020). "Consequently, NKILA promotes the Warburg effect and angiogenesis in gliomas." (PMID 39272133, 2024). "Therefore, NKILA is a potential therapeutic target in gliomas." (PMID 32382013, 2020). "Therefore, we used Cell Counting Kit-8 (Dojindo, Kumamoto, Japan) assays to evaluate whether NKILA could stimulate glioma cell proliferation in vitro." (PMID 32382013, 2020). "In addition, immunohistochemical staining showed that GLUT1, HK2, PKM2, LDH, and MCT1 were significantly downregulated in LN229-K.D.-NKILA group tumors, and also confirmed that decreasing the levels of NKILA inhibited the Warburg effect in glioma cells in vivo, consistent with the in vitro results." (PMID 32382013, 2020). "Therefore, to investigate whether NKILA could stimulate angiogenesis in gliomas, we performed HUVEC tube formation assays." (PMID 32382013, 2020). "Therefore, NKILA modulates the Warburg effect in glioma cells in vitro." (PMID 32382013, 2020).
glioma (continued). "NKILA functions by upregulating HIF-1α expression and the activity of the hypoxia pathway to enhance the Warburg effect and glioma angiogenesis." (PMID 34803608, 2021). "Therefore, understanding how NKILA functions in gliomas may be important." (PMID 32382013, 2020). "To investigate how NKILA modulates the Warburg effect in glioma cells in vivo, we subcutaneously injected LN229-K.D.-NKILA and LN229-K.D.-NC cells into nude mice." (PMID 32382013, 2020). "The results showed that under hypoxia(24 h), the expression of HIF-1α increased dramatically, but NKILA did not change significantly in glioma cells." (PMID 32382013, 2020). "In this study, we found that NKILA stimulates the Warburg effect and angiogenesis in gliomas independent of the NF-kappa B pathway." (PMID 32382013, 2020). "The results showed that there was a significant accumulation of HIF-1α protein in the cells, but the expression of NKILA was not upregulated in glioma." (PMID 32382013, 2020). "The results of HUVEC (human umbilical vein endothelial cell) tube formation assays showed that when Bevacizumab blocked the biological function of VEGFA, glioma cells overexpressing NKILA could not improve the angiogenic ability of endothelial cells as well." (PMID 32382013, 2020).